IL15 (interleukin 15)
Diseases named in the same sentence as IL15 in open-access papers (continued):
Sharing a sentence is not in itself a finding about the gene and the disease.
metabolic syndrome (11 papers, 2015 to 2025). A cluster of metabolic risk factors for CARDIOVASCULAR DISEASES and TYPE 2 DIABETES MELLITUS. "Moreover, IL-15 genetic variants have been linked to an increased risk of CAD and metabolic syndrome (MS)." (PMID 34095164, 2021). "Moreover, we show here that the increased IL-15 levels in VAT of obese individuals correlates with presence of metabolic syndrome." (PMID 26516848, 2015). "Our finding that obese individuals who have met the diagnostic criteria for metabolic syndrome had higher mean levels of IL-1β, IL-6, and IL-15 in VAT than obese individuals without MS also supports this hypothesis." (PMID 26516848, 2015). "We included age, gender (0=male, 1=female), Smoker (0=NO, 1=Yes), Drinker (0=NO, 1=Yes), thyroid-related hormones, IL-6, IL-15, TNF-α, dyslipidemia (0=NO, 1=Yes), and hypertension (0=NO, 1=Yes) as covariates to control for the influence of other relevant factors on LVM." (PMID 38356960, 2024). "Collectively, these data suggest that IL-15 induced by HFD in adipose tissues increase the expression of inflammatory mediators, which in turn perpetuate the inflammatory cascade and promote the development of metabolic syndrome." (PMID 27684068, 2016). "While prior studies have focused on tear cytokines in diabetic retinopathy, our study identified elevated tear cytokines (IL-6, CXCL8, IL-15, CCL5, and VEGF) in diabetic patients without diagnosed retinopathy, persisting after controlling for age, hypertension, and dyslipidemia." (PMID 41030257, 2025).
Thrombocytopenia (11 papers, 2016 to 2025). A reduction in the number of circulating thrombocytes. "For example, high-dose IL-2 has been known to induce fatal capillary leak syndrome, while IL-15 has been associated with hypotension, thrombocytopenia, and other adverse effects included." (PMID 38049832, 2023). "IL-15 also manifested the risk of thrombocytopenia with an evident reduction in platelet and red blood cell counts, whereas biomimetic nanovaccine-mediated IL-15 self-transpresentation displayed no overt toxicity even under the maximum administrable dosage." (PMID 37875481, 2023). "Systemic administration of IL-15 mainly affects NK cells, γδ cells and CD8 memory T cells, but IL-15 can cause symptoms such as hypotension and thrombocytopenia in a dose-dependent manner and can lead to a decrease in neutrophils." (PMID 37404752, 2023). "Although studies have shown that the increase of IL-15 is positively correlated with the survival rate of patients, IL-15 treatment may also cause certain side effects, such as hypotension and thrombocytopenia." (PMID 40625735, 2025). "In cancer patients, infusion of IL-15 leads to dose-limiting toxicities such as hypotension and thrombocytopenia." (PMID 37465665, 2023). "However, due to its adverse effects, such as toxicities, hypotension, thrombocytopenia, IL-15 application was constrained." (PMID 33815365, 2021). "Furthermore systemic administration of IL-15 administration was revealed to have myelosuppressive properties like induction of neutropenia and thrombocytopenia." (PMID 27650544, 2016). "Finally, our findings reveal a pattern of MIS-C-defining molecular features (IL15/IL15RA, MIP1α, TNFα, and IL1 pathways) and clinical and laboratory parameters (thrombocytopenia, eosinopenia, and reduced myocardial function)." (PMID 35577777, 2022).
Allergy (10 papers, 2011 to 2022). An allergy is an immune response or reaction to substances that are usually not harmful. "Also cytokine-deficiencies such as of interleukin 15, which is produced as a mature protein mainly by dendritic cells, monocytes and macrophages, can exacerbate allergy." (PMID 30323863, 2018). "Although the precise role of IL-15 in allergy is not completely understood yet, studies have shown that this cytokine can prevent the development of allergic rhinitis." (PMID 26214693, 2015). "Pathway analysis of the putative PDGF-BB-regulated genes showed that these had highly pleiotropic effects of potential relevance for allergies: B cell signaling, cell migration and proliferation, immune response, and cytokine-related pathways, for example, via IL-6, IL-7, IL-8, and IL-15 signaling." (PMID 35513850, 2022). "Likewise, children with higher value of Interleukin (IL)-15 as well as TNFα-induced protein 3 (TNFAIP3) and Myeloid Derived Growth Factor (MYDGF) at 1 month had lower risk to develop allergy during the 8 year follow-up period." (PMID 33722194, 2021).
alopecia areata (10 papers, 2021 to 2025). Loss of scalp and body hair involving microscopically inflammatory patchy areas. "Aberrant immune responses are considered a major cause of alopecia areata, and interleukin-15 is considered a key factor in the development of the condition." (PMID 38139460, 2023). "Owing to its potent inhibition of interleukin (IL)-15 signaling, ritlecitinib was recently approved in the U. S. and Japan for the treatment of severe alopecia areata." (PMID 40136446, 2025). "In alopecia areata, IL-15 signaling stimulates the survival of CD8+ memory T cells, promotes the proliferation and maintenance of T cells and natural killer (NK) cells, and induces IFN-γ production by CD8+ T cells." (PMID 40136446, 2025). "AA patients also had increased serum levels of IL-15 compared to controls, and even more in patients with alopecia totalis, a severe form of alopecia areata." (PMID 40497955, 2025). "IL-15 is a key cytokine involved in the pathogenesis of alopecia areata, playing a crucial role in amplifying the autoimmune response against hair follicles." (PMID 40284470, 2025). "Another study found that in alopecia areata, various immune cell lineages, including plasmocytoid dendritic cells, NK cells and T cells, along with key molecules such as interferon-γ, interleukin-15, MICA and NKG2D, contribute to the autoimmune process." (PMID 38892934, 2024). "In patients with alopecia areata, an increased serum level of IL-15 compared to healthy controls was described." (PMID 34943905, 2021). "In conclusion, both IL-15 and TNF-α are markers for alopecia areata." (PMID 37206670, 2023).
Alzheimer disease (10 papers, 2015 to 2025). A progressive, neurodegenerative disease characterized by loss of function and death of nerve cells in several areas of the brain leading to loss of cognitive function such as memory and language. "Angiotensinogen, thioredoxin-1 and interleukin-15 had the most prominent associations with Alzheimer’s disease pathology, synaptic and axonal damage markers." (PMID 37680670, 2023). "The role of neuroinflammation in Alzheimer’s disease is pivotal, and among other cytokines, IL-15 has been implicated in the disease pathology and found to be elevated in patients with pathologic β-amyloid status, as in our cohort." (PMID 37680670, 2023). "In Alzheimer’s disease cases, IL-15, IL-1β, IL-6, TNF-α, and IL-8 were higher in those with than without infection." (PMID 33723589, 2021). "Several cytokines (IL-1β, IL-6, TNF-α, IL-8 and IL-15) were further raised in Alzheimer’s disease with systemic infection." (PMID 33723589, 2021). "IL-15 level is raised in the CSF in relation to cognitive impairment and disease progression in Alzheimer’s disease." (PMID 33723589, 2021). "Levels of some cytokines (IL-15 and IL-17A) were highest in brains from Alzheimer’s disease patients with BSV–VI disease." (PMID 33723589, 2021). "Interleukin (IL-15), a pro-inflammatory cytokine has been studied as a possible marker of Alzheimer’s disease (AD); however its exact role in neuro-inflammation or the pathogenesis AD is not well understood yet." (PMID 25710473, 2015). "Multiple brain cytokines were elevated in Alzheimer’s disease and vascular dementia: IL-15 and IL-17A were maximally elevated in end-stage Alzheimer’s disease (Braak tangle stage V–VI) whereas IL-2, IL-5, IL12p40 and IL-16 were highest in intermediate Braak tangle stage III–IV disease." (PMID 33723589, 2021). "Distinct immune markers were found to differentiate FTD from Alzheimer’s disease (AD) and amyotrophic lateral sclerosis (ALS), with GFAP, SPARC, and SPP1 varying between FTD and AD and IL-15, HERV-K, NOD2, and CHIT1 differing between FTD and ALS." (PMID 40305176, 2025). "As shown in the correlation map, IL-15, TRX-1 and AGT had the highest number of significant correlations, after the core Alzheimer’s disease and synaptic biomarkers." (PMID 37680670, 2023). "Another study identified that IL-15 could also serve as a detrimental pro-inflammatory factor in the brain and showed increased serum IL-15 levels, which can be utilized as a biomarker for Alzheimer's disease since IL-15 has been extensively studied in AD pathophysiology." (PMID 37577356, 2023).
Crohn disease (10 papers, 2013 to 2025). A gastrointestinal disorder characterized by chronic inflammation involving all layers of the intestinal wall, noncaseating granulomas affecting the intestinal wall and regional lymph nodes, and transmural fibrosis. "In our previous study on newly diagnosed Crohn’s disease, we observed high levels of IL-15 and IL-23 in healthy mucosa, along with neutrophil infiltration, which are likely the starters of acute inflammation." (PMID 40827526, 2025). "Expression of pro-inflammatory cytokines: IL-1α, IL-1β, TNFα, and IL-15 were increased in IL-1rn-/- mice, and these results are in agreement with those obtained from patients with Crohn's disease." (PMID 31191826, 2019). "An anti-inflammatory role has been suggested for IL-15 cytokine to control TH1 immune responses in Crohn’s disease." (PMID 28168165, 2017). "Similarly, CD127+CD94+ ILCs identified in human lamina propria were reported to secrete granulysin in response to IL-15 and to accumulate in Crohn’s disease patients." (PMID 35300331, 2022). "Therefore, it is conceivable that AhR can be down-regulated by either inflammatory molecules (e.g., IL-15 and Th1 cytokines), which are over-produced in both CD and Crohn's disease, or factors that are differently synthesized in the two disorders." (PMID 30778350, 2019). "Infliximab has been thought to exert its biological functions through blocking TNF, while a recent study found that IL-15 and its soluble receptor might mediate the response to infliximab in patients with Crohn's disease." (PMID 23484133, 2013). "In another study in a murine model of Crohn's disease, UCN could control inflammatory diseases by inhibiting a wide range of inflammatory cytokines such as TNF-α, IFN‐γ, IL-6, IL-1α, IL-1β, IL-12, IL-18, IL-17, and IL-15." (PMID 35419072, 2022). "Moreover, Crohn's disease patients exhibit markedly increased expression of IL15 and IFNγ in the inflamed colon compared with healthy people, indicating that NK1.1+CD8+ T cells involved in intestinal inflammation in Yeti mice might be physiologically relevant to the development of Crohn's disease." (PMID 30333822, 2018).
large granular lymphocytic leukemia (10 papers, 2014 to 2024). "In T-LGL leukemia, hematopoietic failure is caused by BM infiltration of LGLs and release of proinflammatory cytokines, especially IL-15, which is a potent inhibitor of hemopoiesis." (PMID 33445786, 2021). "The underlying mechanism may be that IL-15 causes large granular lymphocytic leukemia by inducing Akt to mediate MDM2 expression, thereby inhibiting the action of the proapoptotic molecule Bid (a member of the Bcl-2 family)." (PMID 39263534, 2024). "Studies which have used immunodeficient mice show that IL-15 can be pro-tumorigenic through the promotion of tumor growth, invasion, and metastasis, overexpression of IL-15 promotes the development of large granular lymphocytic leukemia." (PMID 29255466, 2017). "However, continued stimulation of NK-cell activation by IL-15 leads to severe large granular lymphocytic leukemia." (PMID 39263534, 2024). "Similarly, in LGL leukemia, IL-15 is overexpressed, and chronic exposure of normal LGLs to IL-15 induces leukemic transformation with chromosomal and centrosome abnormalities." (PMID 33445786, 2021). "Consistently, when we triggered STAT3 phosphorylation with IL-6 (20 ng/ml) or IL-15 (20 ng/ml), key cytokines in LGL leukemia development, after one hour culture we observed an increase of Fas ligand transcription levels (1.59- and 2.01-fold after IL-6 and IL-15, respectively)." (PMID 28977911, 2017). "IL2 and IL15 activate lymphoproliferative signaling through JAK1/JAK3-STAT3/STAT5 and IL15 has shown to be elevated in large granular lymphocytic leukemia." (PMID 29228628, 2017).
metastatic disease (10 papers, 2013 to 2024). "NK cells with deficient expression of OPN display defective responses to IL-15 and diminished responses to metastatic tumors." (PMID 37032358, 2023). "Administration of recombinant human IL-15 to patients with metastatic disease was safe and caused efflux of NK cells from the circulation within 30 min followed by massive hyperproliferation by 48 h and return to baseline up on cessation of IL-15 administration." (PMID 33782423, 2021). "Several preclinical studies have demonstrated the important role of IL-15 in controlling metastatic disease, and combinations with immune checkpoint inhibitors (ICIs) have been proven beneficial." (PMID 36713398, 2022). "Clinical trials with recombinant IL-15 or IL-15/IL-15Rα complexes are being conducted in metastatic tumors." (PMID 36560427, 2022). "Platelet count, IL-15 and GM-CSF are potential prognostic indicators of metastatic disease in PDAC patients from our local South African population." (PMID 35020761, 2022). "In earlier studies, IL-15 combined with cyclophosphamide showed better survival and control of metastatic disease in an IV model of rhabdomyosarcoma providing the initial supportive findings of these therapeutic modalities." (PMID 36713398, 2022). "The QuEST1 study showed that the triple-hit approach of BNVax (a therapeutic poxviral vaccine targeting brachyury), anti-PD-L1 monoclonal antibodies, and interleukin-15 superagonist complexes have eradicated traces of bone detectability of bony metastasis in two patients with metastatic disease." (PMID 36835981, 2023). "By means of multivariate logistic regression analysis, we built a combined biomarker model of these three circulating biomarkers (platelet count, IL-15 and GM-CSF) that discriminates metastatic PDAC from non-metastatic disease." (PMID 35020761, 2022). "Both IL-15 and IL-6 were elevated in patients with metastatic disease compared to patients with non-metastatic disease, as was identified via comparing levels in the first available serum sample across cohorts." (PMID 36831406, 2023). "Preclinical studies have shown that IL-15 enhances CTL responses in murine tumor models and the administration of IL-15 in combination with anti-PD-L1and anti-CTLA-4 antibodies showed greater cytolytic and effector functions on the CD8+ T cells of metastatic tumor-bearing animals." (PMID 26344343, 2013). "However, the difference between resectable disease and metastatic disease was not significant for IL-15." (PMID 36831406, 2023).
non-Hodgkin lymphoma (10 papers, 2010 to 2025). Distinct from Hodgkin lymphoma both morphologically and biologically, non-Hodgkin lymphoma (NHL) is characterized by the absence of Reed-Sternberg cells, can occur at any age, and usually presents as a localized or generalized lymphadenopathy associated with fever and weight loss. "Another study demonstrated that transferring of ex vivo expanded autologous NK cells with IL-15 was potent regression in non-Hodgkin lymphoma (NHL) patients." (PMID 33652996, 2021). "HLA-mismatched NK cells isolated from UCB and transfected with a retrovirus-based vector expressing anti-CD19 CAR, iCaspase-9, and IL-15 were administered in 11 patients with CLL or non-Hodgkin’s lymphoma." (PMID 33287875, 2020). "Higher levels of IL-15 on Day 15 post- autologous hematopoietic stem cell transplant (HSCT) have been shown to directly correlate with improved overall survival (OS) in patients with relapsed non-Hodgkin lymphoma (NHL)." (PMID 30805309, 2019). "In a phase 1 trial of patients with relapsed or refractory non-Hodgkin lymphoma (NCT03019666), the adoptive transfer of NK cells cultured with IL-15 and nicotinamide in combination with rituximab showed a complete response in 13 of 19 patients, with NK cells detected 14 days post-infusion." (PMID 38223411, 2024). "Another study demonstrated that in patients with non-Hodgkin lymphoma (NHL), autologous NK cells expanded ex vivo with IL-15 could effectively induce remission." (PMID 39682724, 2024). "The IL-15 superagonist complex N-803 (formerly termed ALT-803) induces potent activation of NK cells and has been shown to be safe when administered alone and in combination with the anti-CD20 antibody rituximab in patients with indolent non-Hodgkin lymphoma." (PMID 38223411, 2024).
non-small cell lung carcinoma (10 papers, 2015 to 2024). A group of at least three distinct histological types of lung cancer, including non-small cell squamous cell carcinoma, adenocarcinoma, and large cell carcinoma. "In vitro stimulation of terminally exhausted CD8+ TIL from non-small-cell lung cancer patients with IL-15 rescued lymphocyte responsiveness to PD-1 blockade and enhanced proliferation." (PMID 33679747, 2021). "In a phase I clinical trial evaluating the safety of the intravenous administration of allogeneic NK cells combined with chemotherapy, researchers treated non-small-cell lung cancer (NSCLC) patients with allogeneic NK cells expanded ex vivo using IL-15 and hydrocortisone." (PMID 39682724, 2024). "Further optimization of the constructs might safely regulate the secretion of IL-15 and a clinical trial of NK cells genetically engineered to secrete low concentrations of IL-15 was recently initiated in patients with r/r non-small cell lung cancer (NCT05334329)." (PMID 39430751, 2024).
anemia (9 papers, 2016 to 2023). A reduction in the number of red blood cells, the amount of hemoglobin, and/or the volume of packed red blood cells. "IL-15 contributes to the development of anemia in mediating the suppression of erythropoiesis by IFN-γ." (PMID 37836388, 2023). "They found that elevated circulating levels of MCP-1, IL-2R, IL-15, and IL-8 predicted poor anemia response and that increased levels of sIL-2R, IL-15, and MCP-1 clustered with splenomegaly, which in turn associated with impaired hemoglobin raise during treatment." (PMID 32967342, 2020). "However, the chronic and excessive production of IFNG or repetitive supplementation with downstream cytokines (e.g. IL15) induces cell exhaustion, bone marrow failure, accompanied by anemia." (PMID 32905461, 2019). "Bone marrow hypocellularity, anemia and severe neutropenia have been observed in macaques treated daily with human recombinant IL-15 by subcutaneous injection and, more importantly, recently similar side effects have been observed in first in human clinical trial of recombinant-IL15." (PMID 27356750, 2016).
cutaneous T-cell lymphoma (9 papers, 2013 to 2023). "Depending on the promoters, genetic background and expression levels, IL-15 mice show either altered immunity or development of aggressive T-/NK- cell leukemia, and cutaneous T-cell lymphoma." (PMID 37153603, 2023). "Preliminary Phase I data clarified that BNZ-1 was well tolerated and inhibited IL-2 and IL-15 activity, leading to clinical improvement in participants with cutaneous T-cell lymphoma (CTCL) by rejuvenating anti-lymphoma immunity and reducing inflammatory responses (NCT03239392)." (PMID 37483629, 2023). "In cutaneous T-cell lymphoma, upregulation of HDAC1 and HDAC6 was detected as a result of excessive autocrine production of IL-15 driven by disruption of the Zeb1 transcription factor binding to the IL-15 promoter." (PMID 35887172, 2022).